MMP9 (matrix metallopeptidase 9)
Diseases named in the same sentence as MMP9 in open-access papers (continued):
Sharing a sentence is not in itself a finding about the gene and the disease.
acne (13 papers, 2017 to 2025). An inflammatory process of the sebaceous glands which is characterized by comedones, nodules, papules and/or pustules on the skin. "Along with using IPL alone for the treatment of moderate to severe MGD, IPL treatment using the acne filter is a promising alternative for MGD treatment in terms of reduction in MMP-9 positivity." (PMID 39797282, 2025). "IPL treatment using acne filter is a promising treatment option for reducing MMP-9 positivity in MGD patients." (PMID 39797282, 2025). "Significantly increased expression of TLR-4, IL-2, IL-10, and TIMP-2 and decreased MMP-9 havebeen demonstrated in patients with acne prone to scarring." (PMID 38398480, 2024). "Isotretinoin, quercetin, and daylight photodynamic therapy are all effective acne therapies that have been shown to decrease MMP9 expression." (PMID 38321132, 2024). "C. acnes can increase the production of several MMPs, such as MMP-1, MMP-9, and MMP-13, and a correlation between elevated levels of MMP-9 and the number of acne-induced skin lesions, e.g., pustules, has been reported." (PMID 39744637, 2024). "Minocycline, a tetracycline antibiotic used to treat acne in adolescence, has been reported to decrease matrix metallopeptidase-9 (MMP9) level that is too high in FXS." (PMID 37420260, 2023). "The Zn-de-Model group exhibited higher levels of these cytokines than the Model group, with increases of 51.74% for TNF-α, 11.91% for IL-1β, 118.06% for IL-17A, 19.64% for MMP9, and 17.05% for CXCL1/KC, indicating that Zn deficiency leads to more severe skin inflammation in acne-like mice." (PMID 40507073, 2025). "As one of the major pathogeneses of acne, P. acne was reported to induce the production of MMP9." (PMID 38321132, 2024). "Increased MMP9 levels are correlated with both the severity of acne and the size of inflammatory lesions, making it a potential biomarker for identifying the best course of therapy for acne." (PMID 39347283, 2024). "Tear MMP-9 positivity significantly decreased in the acne filter group alone (p = 0.032)." (PMID 37095152, 2023). "Specifically, the modulation of EGFR and various MMPs (MMP1, MMP2, MMP9, and MMP13) through the relaxin signalling pathway appears to be a pivotal mechanism by which P. pterocarpum exerts its anti-acne effects." (PMID 39347283, 2024). "The core targets - EGFR, MMP1, MMP2, MMP9, and MMP13 - that directly participate in the relaxin signalling pathway are useful in managing acne by targeting these core targets." (PMID 39347283, 2024). "Among the 21 common targets of P. pterocarpum and acne, five targets - EGFR, MMP1, MMP2, MMP9, and MMP13 - were selected as the core targets because of their direct involvement in the relaxin signalling pathway." (PMID 39347283, 2024). "Keratinocytes are an important source of MMPs in acne vulgaris, and P. acnes can induce the expression of several kinds of MMPs, including MMP-2 and MMP-9." (PMID 33082712, 2020). "Moreover, there are indications that C. acnes enhances the activity of various MMPs, including MMP-1, MMP-9, and MMP-13, which have been detected in the sebum of acne patients." (PMID 40332093, 2025). "In acne lesions, all hub genes were negatively correlated with resting mast cells, whereas 9 (except CXCL10), 9 (except MMP9) and 8 (except MMP9 and CXCL10) hub genes were positively correlated with activated mast cells, gamma delta T cells, and neutrophils, respectively." (PMID 38321132, 2024). "A few types of MMPs were found in the sebum of acne patients, including MMP-1, MMP-13, and MMP-9." (PMID 35329904, 2022). "Similarly, our current study showed that IPL with an acne filter had an improved therapeutic effect on the TBUT, ocular staining scores, lid margin telangiectasia, lid meibum expressibility, lid meibum secretion score, LWE staining grade, and tear MMP-9 level." (PMID 37095152, 2023).
acne (continued). "Significantly elevated MMP-9 levels were also found in the blood of acne patients and a correlation between MMP-9 levels and the extent of facial inflammatory lesions was revealed, though no direct link was established between MMP-9 and scarring." (PMID 40332093, 2025).
acute pancreatitis (13 papers, 2008 to 2025). An acute inflammatory process that leads to necrosis of the pancreatic parenchyma. "In addition, a clinical report implicated MMP-9 in increased end-organ injury during acute pancreatitis." (PMID 34830195, 2021). "MMP9 rs3918242 has been associated with the risk of spontaneous deep intracerebral hemorrhage, potentially malignant and malignant lesions of the head and neck, and has served as a biological indicator of the efficacy of ulinastatin in the treatment of patients with severe acute pancreatitis." (PMID 38004080, 2023). "MMP-9 is involved in the degradation and remodeling of the extracellular matrix and the pathogenesis of acute pancreatitis." (PMID 34830195, 2021). "This is in line with the notion that MMP8 and MMP9 are expressed by neutrophils and with previous reports that plasma MMP9 is increased in acute pancreatitis." (PMID 23442769, 2013). "In another study, serum matrix metalloproteinase 9 (MMP9) levelin severe acute pancreatitis was positively correlated with TNFα and CRP levels." (PMID 18670651, 2008). "The mechanism by which the chymase inhibitor decreased the neutrophil infiltration of acute pancreatitis might depend on inhibiting MMP-9 activation in the pancreas." (PMID 34830195, 2021). "The aim of this study was to investigate the effects of hypoxia-inducible factor-1α (HIF-1α) and matrix metalloproteinase-9 (MMP-9) on alveolar-capillary barrier disruption and lung edema in rat models of severe acute pancreatitis-associated lung injury (PALI)." (PMID 25120621, 2014). "Several researches have been linking the upregulation of MMP-9 by TNF—α expression, and the levels of these two mediators have been correlated with the severity of acute pancreatitis." (PMID 35041718, 2022).
bladder tumor (13 papers, 2012 to 2023). "Previous reports have demonstrated that MMP-9 is associated with the migration and invasion processes of bladder tumors." (PMID 28680385, 2017). "Previous reports demonstrated that MMP-9 expression was closely associated with bladder tumor invasion and migration." (PMID 22962576, 2012). "The ability of SPHF to impede transcription-factor-mediated MMP-9 expression suggests that it likely disrupts the migration and invasion of bladder tumors." (PMID 32708058, 2020). "Furthermore, expression of MMP-9 (gelatinase B, a 92-kDa gelatinase) is closely related with the migration and invasion ability of bladder tumor cells via the activation of transcription factors, including AP-1, Sp-1, and NF-κB." (PMID 28680385, 2017). "Additionally, it downregulates matrix metalloprotease-9 (MMP-9) mRNA as well as the MMP-9 translational protein in murine bladder tumors." (PMID 22778725, 2012). "Profiling the secretome of adipocytes obtained from bladder tumor samples using a human cytokine/chemokine panel revealed high levels of CCL3 (macrophage inflammatory protein-1α) and matrix metalloproteinase-9 (MMP9)." (PMID 37569686, 2023). "In total, five articles investigating four different MMPs types (MMP1, MMP7, MMP9, and MMP11) reported a relationship between abnormal levels of MMPs and bladder tumor progression." (PMID 28427222, 2017). "In the animal experiment, MSCs could favor VX2 bladder tumor growth and up-regulate the expression of TGFβ1, EGF, FAPa, MMP9 in VX2 tumor tissue." (PMID 31528217, 2019). "Taken together, we suspected that CD164 could promote the migration and invasion of bladder tumor cells through regulating relevant proteins including MMP2 and MMP9." (PMID 30022623, 2018). "Indeed, metastatic bladder tumor cells do have lower catalase activity, compared to non-metastatic counterparts, leading to the induction of redox-sensitive pro-tumorigenic and pro-metastatic genes, such as VEGF and matrix metalloproteinase 9 (MMP-9)." (PMID 34073079, 2021).
bone cancer (13 papers, 2014 to 2025). A primary or metastatic malignant neoplasm affecting the bone or articular cartilage. "By applying this approach to data obtained from cell line models, clinical samples, and xenograft mouse models, the study revealed the crucial role of ERK5/MMP-9 signaling as a driver of metastasis in primary bone cancer." (PMID 37601096, 2023). "Our results implicate a newly discovered, multidimensional MAPK7/MMP9 signalling hub in primary bone cancer metastasis that is clinically actionable." (PMID 32655131, 2020). "In conclusion, in this mouse model of bone cancer pain YKS significantly lessened cancer pain behavior by suppressing MMP-9 expression, suppressing the expression in bone tissue in the early phase and in the spinal cord in the late phase of pain development." (PMID 31239855, 2019). "Another study analyzing patient and mice tumors using RNA sequencing collectively support that MAPK7/MMP9 (matrix metallopeptidase 9) is responsible for inducing the primary bone cancer progression resulting in tumor/metastasis growth, colony formation, and macrophage polarization." (PMID 36769180, 2023). "The acquisition of lower concentrations of MMP-2 and MMP-9 in patients with this bone cancer is surprising; however, it may indicate the potential of these compounds in the diagnosis and prognosis of OS patients." (PMID 38138968, 2023). "This approach with comparisons applied to data collected from cell line models, clinical samples and xenograft mouse models revealed mitogen-activated protein kinase 7/matrix metallopeptidase 9 (MAPK7/MMP9) signalling as a driver for primary bone cancer metastasis." (PMID 32655131, 2020). "Furthermore, it is also important to clarify which component of YKS plays a crucial role in alleviation of bone cancer pain and MMP-9 suppression." (PMID 31239855, 2019). "Bone colonizing PC-3 cells induce the expression of active MMP-9 at earlier time periods suggesting that CXCL12/CXCR4-mediated homing of PC cells to bone would functionally link with the expression of MMP-9 in local bone tumor microenvironment and induce invasive bone tumor growth." (PMID 24472670, 2014). "We identified 73 overlapping genes between ATBC exposure and bone cancer, subsequently prioritizing STAT3, EGFR, MMP9, MAPK1, and MMP2 as core targets." (PMID 40625361, 2025). "This study underscores the potential carcinogenic effects of ATBC in bone cancer, identifying key targets such as STAT3, EGFR, MMP9, MAPK1, and MMP2." (PMID 40625361, 2025). "This subtype is mostly found in progressive primary bone tumors as well as in metastatic sites, resulting in increased angiogenesis via the secretion of VEGF and matrix metallopeptidase (MMP9), which help to promote tumor growth and proliferation." (PMID 36769180, 2023). "CD147 expression levels were markedly up-regulated over half of the expression levels in the benign bone tumor tissues as well as the MMP-2 and MMP-9 expression levels." (PMID 30043854, 2018). "Notably, among these core targets, STAT3, EGFR, MMP9, MAPK1, and MMP2 were identified as the top five targets based on MCC values, serving as the hub targets of ATBC-induced bone cancer." (PMID 40625361, 2025). "The same study also found lower levels of MMP-9 in cancer patients, while MMP-9 levels were independent of gender, age, location, and bone tumor size." (PMID 38138968, 2023).
cerebrovascular diseases (13 papers, 2009 to 2025). "This may be due to the fact that HCRP and MMP9 are not only important pathological products but also direct pathogenic factors of cardiovascular and cerebrovascular diseases." (PMID 23606891, 2013). "MMP-9 plays a significant role in the pathogenesis of various cerebrovascular diseases, with elevated MMP-9 levels consistently correlating with poor clinical prognosis." (PMID 40284474, 2025). "Several studies have investigated MMP-9-related nanomedicines in cerebrovascular diseases." (PMID 40284474, 2025). "Among all MMP subtypes, MMP-2 and MMP-9 are the most studied MMPs in cerebrovascular disease." (PMID 26581247, 2015).
Chagas disease (13 papers, 2013 to 2025). A parasitic infection caused by Trypanosoma cruzi. "Here, we characterize the MMP-2 and MMP-9 gelatinases as putative biomarkers of the evolution of clinical forms in Chagas disease." (PMID 31578449, 2019). "In human Chagas disease, MMP-2 has been previously associated with regulatory responses in IND patients by correlations with regulatory cytokines, especially IL-10, whereas MMP-9 has been associated with inflammatory response and cardiomyopathy." (PMID 31578449, 2019). "used multiplex analysis of serum samples (participants classified by the New York Heart Association) to show that the MMP-2/MMP-9 ratio increased with the severity of cardiac disease, where patients with severe cardiac Chagas disease presented with increased levels of MMP‐9 compared with MMP‐2." (PMID 35895410, 2022). "We have pointed out that MMP-2 and MMP-9 together can predict clinical evolution in Chagas disease." (PMID 31578449, 2019). "In conclusion, our results point out that MMP-2 and MMP-9 together could be a tool for predicting clinical evolution in Chagas disease." (PMID 31578449, 2019). "On the other hand, T. cruzi derived-antigens promote a differential expression of MMP-2 and MMP-9 in patients with Chagas disease and may regulate MMPs expression in neutrophils and monocytes, mainly when a cardiac alteration is not present." (PMID 28118356, 2017). "Our results demonstrate that sCD40L and MMP-9 are increased in both Chagas disease and VL." (PMID 23870715, 2013). "Thus, both sCD40L and MMP-9 levels were evaluated in sera of Chagas disease and VL patients compared with those found in non endemic controls." (PMID 23870715, 2013). "Particularly in Chagas Disease, neutrophils and monocytes show differential expression of MMP-2 and MMP-9 in the bloodstream." (PMID 33891967, 2021). "Due this dichotomous characteristic in the activation of IL-1β in patients with different clinical forms of Chagas' disease, we propose MMP-2 and MMP-9 as potential biomarkers of prognostic which should be better investigated." (PMID 31057540, 2019). "In vitro stimulation with T. cruzi-derived antigens induces higher MMP-2 and MMP-9 expression in monocyte from patients with cardiac clinical forms of Chagas disease compared with those from non-infected patients." (PMID 29375564, 2017). "In Chagas disease patients, T cells, neutrophils and monocytes are source of MMP-2 and MMP-9." (PMID 29375564, 2017).
tendinopathy (13 papers, 2011 to 2025). "Although the exact pathway is unknown, we speculate that the NOX family, which has been previously reported to regulate the levels of various MMPs, may delay tendon healing by increasing the levels of tendinopathy-associated MMPs such as MMP9 and MMP2." (PMID 38247510, 2024). "By intersecting the targets of NGR1 with those associated with tendinopathy, we constructed a PPI network, and the results showed that targets such as IL-6, TNF, AKT1, MMP9, and MMP3 are valuable in assessment." (PMID 40697661, 2025). "In the context of tendinopathy, MMP9 is particularly important due to its ability to degrade collagen, a primary structural component of tendons." (PMID 40697661, 2025). "Previous research has indicated that TIMP-1 hinders excessive matrix degradation by impeding MMP activity, especially that of MMP-9, as MMP-2 and MMP-9 are upregulated in tendinopathies." (PMID 38247510, 2024). "In the severe tendinopathy group, there was higher expression of MMP9 and IL-1β in media containing PRP." (PMID 36769065, 2023). "Network-based assessment indicated that key targets associated with NGR1 in treating tendinopathy may potentially include IL-6, TNF, and MMP9." (PMID 40697661, 2025). "Increased expression of Mmp2 and Mmp9 was not only seen in tendinopathy, but also during aging." (PMID 35008516, 2021). "Also, core‐resident “tenophage” or “tenoclast” populations have recently been gaining more attention as potential role players in early tendinopathy, especially in combination with increased expression of Tnf‐α, Il‐6, Mmp‐3, and Mmp‐9." (PMID 34494401, 2021). "In contrast, MMP1 was upregulated in human patellar tendinopathy and increased expression of MMP1 was found in tendon ruptures Additionally, upregulation of MMP2 and MMP9 was shown to be a feature of tendinopathy and increased MMP9 activity was seen after exercise." (PMID 35008516, 2021). "In addition, a significant increase in the expression of Cox2, Mmp2, Mmp9, Col1a1, Col3a1, Vegf and Scx genes was also observed within the experimentally induced tendinopathy group compared with the control group." (PMID 33076550, 2020). "In addition to MMP-2 and MMP-9, MMP-3 has been found to be dysregulated during tendinopathies, which is inconsistent with its expected role in matrix remodeling." (PMID 38247510, 2024). "Abnormal extracellular matrix (ECM) remodeling was a key characteristic and pathological progress in tendinopathy, and increased COL I, COL III, MMP3 and MMP9 expression as well as decreased COL III/COL I rate and TIMP-1 content were detected in the tendinopathy mice." (PMID 36604715, 2023). "The gelatinase MMP2 was significantly upregulated in the tendinopathy and chronic rupture group compared to the intact and acute ruptured tendons, but MMP9 was not affected." (PMID 29385715, 2018). "Furthermore, the molecular docking results presented the stable and high-affinity binding of NGR1 to TNF-α, IL-6, MMP3, MMP9, and MMP13, indicating that NGR1 may exert its therapeutic effects on tendinopathy by modulating inflammatory responses and cellular and extracellular matrix metabolism." (PMID 40697661, 2025).
thrombosis (13 papers, 2011 to 2025). "Malaponte and coauthors determined that the CC genotype of MMP-9 rs3918242 was linked to deep vein thrombosis in cancer patients." (PMID 40724896, 2025). "Few studies have hitherto assessed the role of MMP9 in thrombosis and its specific mechanism in increased susceptibility to VTE formation in SS patients." (PMID 38029239, 2023). "Specifically, MMP-9 levels rise during acute thrombosis and decrease upon resolution, suggesting a role in thrombus breakdown." (PMID 40299499, 2025). "Accordingly, directly or indirectly regulating the expression level of MMP9 represents a novel approach to treating venous thrombosis." (PMID 38029239, 2023). "It has been established that the anticoagulant edoxaban can regulate thrombosis factors, improve venous lesions, and inhibit venous thrombosis through MMP9-induced PI3K/AKT signaling pathway." (PMID 38029239, 2023). "Under conditions of ferric chloride-induced venous thrombosis, edoxaban leads to upregulation of hydrogen sulfide and homocysteine activities through the MMP-9-induced PI3K/AKT signaling pathway." (PMID 37261475, 2023). "IFN-γ can induce the formation of NETs by neutrophils with subsequent venous thrombosis development and delay thrombus resolution by inhibiting MMP-9 production by monocytes." (PMID 35444662, 2022). "Patients with deep venous thrombosis have marked increases (>4 fold) in circulating MMP-9, supporting its importance in clinical thrombus resolution." (PMID 26406902, 2015). "Among them, F2, MMP9, CXCL12, and MET are also the seed nodes in the network cluster analysis and have been shown that they have a multi-dimensional connection with thrombosis." (PMID 34433871, 2021). "When the plaque was analysed as a whole, rather than specifically in areas of hemorrhage or thrombosis, high concentrations of MMP-9 were detected in normal tissues and in asymptomatic surgical specimens." (PMID 21457581, 2011). "However, MMP-9 did not influence endothelial cell ingrowth after venous thrombosis." (PMID 26406902, 2015).